GSK3A (glycogen synthase kinase 3 alpha)
Diseases named in the same sentence as GSK3A in open-access papers (continued):
Sharing a sentence is not in itself a finding about the gene and the disease.
prostate carcinoma (8 papers, 2014 to 2025). A carcinoma that arises from epithelial cells of the prostate gland. "Nevertheless, we recognize the significance of GSK3α, and future studies should explore its role and the possible impacts of its inhibition in prostate cancer cells." (PMID 40072085, 2025). "Overall, our data demonstrated the isoform specific role of GSK3α and GSK3β in prostate cancer cells in vitro, and tumor growth and micrometastasis in vivo, via distinct molecular and cellular mechanisms." (PMID 25714023, 2015). "This was in agreement with the clinical report from human prostate cancer patient tumor tissues indicating increased protein and mRNA expression of GSK3α starting from the early tumor growth and increased expression of GSK3β specifically in advanced cancers." (PMID 25714023, 2015). "Together, these results indicated that both GSK3α and GSK3β isoforms are necessary for the prostate cancer cell motility and invasion." (PMID 25714023, 2015). "Our results indicated that prostate cancer cell proliferation is predominantly regulated by GSK3α isoform." (PMID 25714023, 2015). "This suggested distinct roles for GSK3α and GSK3β in the early and later stages of prostate cancer growth." (PMID 25714023, 2015). "ShRNA-mediated knockdown of GSK3α and GSK3β equally inhibited the ability of prostate cancer cells to migrate and invade the endothelial-barrier in vitro, and PC3 cell micrometastasis to lungs in vivo." (PMID 25714023, 2015). "From our in vitro studies, we know that silencing GSK3α predominantly inhibits prostate cancer cell proliferation." (PMID 25714023, 2015). "Nevertheless, we provide the first report on the isoform specific function of GSK3α and GSK3β in the regulation of prostate cancer cell survival and proliferation, as well as EMT and micrometastasis, respectively." (PMID 25714023, 2015). "Glycogen synthase kinase 3 (GSK-3), a serine-threonine kinase is one of the least characterized substrate of Akt in prostate cancer cells, whose activity is inhibited by Akt via phosphorylation at serine 9 and 21 in GSK-3α and GSK-3β isoforms, respectively." (PMID 24519956, 2014). "Compared to normal prostate, GSK-3α and GSK-3β were up-regulated in prostate cancer with GSK-3α elevated in low Gleason tumors and GSK-3β expressed in high Gleason tumors." (PMID 24519956, 2014). "Our analysis of 22Rv1 stem/progenitor cell marker gene expression revealed a small increase in NANOG and reduction in SOX2 in GSK-3α-silenced cells, inconsistent with selection for prostate cancer stem/progenitor-like cells." (PMID 25327559, 2014). "However, the observed functional overlap between GSK3α and GSK3β gene silencing on cell motility, invasion and micrometastasis in vivo questioned if prostate cancer metastasis is a redundant function of both the GSK3 isoforms." (PMID 25714023, 2015). "Hence, we next determined the effect of isoform specific knockdown of GSK3α and GSK3β in prostate cancer cells on their motility and transendothelial migration (microinvasion)." (PMID 25714023, 2015). "Interestingly, expressions of both GSK3 isoforms were elevated in advanced prostate cancer tissues further indicating that GSK3α may also be needed in advanced prostate cancer." (PMID 25714023, 2015). "Transfection with shRNA targeting GSK3α in PC3, DU145, and LNCaP prostate cancer cells represses proliferation, survival, and colony formation in cell cultures and the tumor expansion of xenografts in athymic nude mice." (PMID 33339170, 2020). "In the current study, we provide the first evidence that the regulation of cell survival, proliferation and rate of tumor growth in early (LNCaP) and advanced prostate cancer (PC3 and DU145) cells are predominantly dependent on GSK3α." (PMID 25714023, 2015). "Thus, our results demonstrated that GSK3α, and not GSK3β is necessary for the prostate cancer cell proliferation, survival and colony formation in vitro and tumor xenograft growth in vivo." (PMID 25714023, 2015).
prostate carcinoma (continued). "We report that silencing of GSK3α, but not GSK3β expression inhibited proliferation, survival and colony formation by the PC3, DU145 and LNCaP prostate cancer cells, and the growth of PC3 tumor xenografts in athymic nude mice." (PMID 25714023, 2015). "In order to determine the isoform specific role of GSK3 in the regulation of prostate cancer cell growth and proliferation, we generated PC3, DU145 and LNCaP stable cell lines expressing ShRNAs for control (non-target), GSK3α and GSK3β (ShControl, ShGSK3α and ShGSK3β, respectively)." (PMID 25714023, 2015).
colon carcinoma (7 papers, 2014 to 2023). "GSK3α was more closely associated with colon cancer progression and unfavorable outcomes than GSK3β." (PMID 37031867, 2023). "We performed ChIPseq using HCT116 colon carcinoma cells, identifying ~850 putative target genes associated with metabolism (e.g., Prdx5, Mdh1, Ahcy), transcription (Taf12, Tet2, histones), malignancy (Met, Blcap, Rras, Jag1, Gsk3a) and mitotic stability (Zbtb4)." (PMID 31059499, 2019). "First, the roles of GSK3α-regulated phosphosites remain to be disclosed, especially those whose levels are significantly correlated with the OS of colon cancer patients." (PMID 37031867, 2023). "To decipher the roles of GSK3α in colon cancer, we profiled the in vitro and cellular phospho-substrates of GSK3α and identified 156 phosphosites specifically regulated by GSK3α but not GSK3β." (PMID 37031867, 2023). "Collectively, these results indicate that GSK3α is an important kinase in colon cancer and that high expression of GSK3α predicts unfavorable OS in colon cancer patients." (PMID 37031867, 2023). "In summary, we investigated the kinase functions of GSK3α and its specific phospho-substrates in colon cancer." (PMID 37031867, 2023). "Collectively, this work not only discloses the specific function of GSK3α as a kinase but also suggests GSK3α as a promising therapeutic target for colon cancer." (PMID 37031867, 2023). "To decipher the roles of GSK3α in colon cancer, we profiled the phosphorylation substrates of GSK3α and uncovered 156 phosphosites from 130 proteins specifically regulated by GSK3α." (PMID 37031867, 2023). "To further confirm the clinical significance of GSK3α, we next performed immunohistochemical straining of colon cancer tissue microarrays from another independent colon cancer cohort using a specific anti-GSK3α antibody." (PMID 37031867, 2023). "In the vast majority of samples, FAK/p-GSK3α/βY279/Y216/β-catenin (19 of 26 samples) and PYK2/p-GSK3α/βY279/Y216/β-catenin (18 out of 26 samples) were regulated in the same way, supporting that they are related events in the development of colonic cancer." (PMID 26274564, 2015). "We showed that GSK3α and GSK3β differ greatly in their binding proteins and phospho-substrates in colon cancer cells, although we cannot exclude the possibility that the phospho-substrates of GSK3α and GSK3β may differ in different cell types." (PMID 37031867, 2023). "Collectively, these results suggest that the high expression of GSK3α in tumors is disastrous and may promote colon cancer malignancy." (PMID 37031867, 2023). "Third, we investigated the potential roles of THRAP3S248p, a phosphosite regulated by GSK3α, in colon cancer and showed that THRAP3S248p may function in the regulation of colon cancer cell migration and DDR." (PMID 37031867, 2023). "As expected, high levels of GSK3α were also significantly correlated with unfavorable prognosis in colon cancer patients, whether in 111 tumors of different stages or in tumors of stage II, III, and IV alone." (PMID 37031867, 2023). "Therefore, by using WT and GSK3A-KO colon cancer cell lines, we screened phospho-substrates exclusively regulated by GSK3α in cell lines with three biological repeats." (PMID 37031867, 2023). "Furthermore, a number of phospho-substrates of GSK3α have been identified in tissues from colon cancer patients and some of them show a significant correlation with the OS of colon cancer patients." (PMID 37031867, 2023). "•High levels of GSK3α predict poor prognosis of colon cancer patients." (PMID 37031867, 2023). "To confirm that GSK3A inhibition re-sensitize drug-resistant colon carcinoma cells to chemotherapy, we then treated three cell lines characterized by different genetic background, HCT116p53KO, SW480 and HT-29 drug-resistant cells, with 5FU in the presence of 20 μM SB216763 and 1 μM BIO." (PMID 24984063, 2014).
colon carcinoma (continued). "Moreover, stable silencing of GSK3A expression reverted the resistance also to OxPt treatment, another DNA-damaging drug commonly used in colon carcinoma therapy." (PMID 24984063, 2014). "To test the role of GSK3A in colon carcinoma cells we first established a stable cell line depleted of the protein by transducing drug-resistant HCT116p53KO cells with retroviruses expressing shRNAs to GSK3A." (PMID 24984063, 2014). "Therefore, we assume that specific inhibition or targeted degradation of GSK3α by proteolysis-targeting chimeras may be an effective strategy for the treatment of colon cancer." (PMID 37031867, 2023). "Notably, in the tumors of colon cancer patients grouped into high-GSK3α based on the best cutoff, the expression differences of GSK3α between tumors and DNTs were much more significant, although some stages were no longer significant after TNM staging, probably due to the limited number of samples." (PMID 37031867, 2023). "In contrast, high levels of GSK3α in tumors were significantly positively associated with poor prognosis in colon cancer, whether in 74 tumors of different stages or in tumors of stage II, III, and IV alone, indicating that GSK3α is a key kinase in colon cancer." (PMID 37031867, 2023). "Overlapping analysis revealed that only GSK3α and MAP2K1 could predict the prognosis of colon cancer patients in stages II-IV." (PMID 37031867, 2023). "In this study, unexpectedly, we found that the expression of GSK3α, but not GSK3β, was significantly correlated with the overall survival of colon cancer patients in 4 independent cohorts." (PMID 37031867, 2023). "First, we demonstrated that high expression of GSK3α, but not GSK3β, was significantly correlated with unfavorable outcomes in colon cancer patients from four independent cohorts." (PMID 37031867, 2023). "Yet, our research has revealed that GSK3α, rather than GSK3β, is significantly correlated with colon cancer patients' survival." (PMID 37031867, 2023). "Based on our proteome and immunostaining data and publicly available proteome data from 4 independent colon cancer cohorts, we showed that GSK3α, but not GSK3β, was able to predict the prognosis of colon cancer patients." (PMID 37031867, 2023). "Second, we identified 156 phospho-substrates specifically regulated by GSK3α, but not GSK3β, in vitro and in colon cancer cell lines." (PMID 37031867, 2023).
depression (7 papers, 2009 to 2024). "GSK3α/β knock-in mice showed increased stress-induced depression-like behaviors, while inhibiting the activity of GSK3β reduced depression symptoms." (PMID 36776771, 2022). "Notably, in our experiments, the chronic lithium treatment known to amplified GSK3α phosphorylation at serine 21 and GSK3β at serine 9, is able to reverse the behavioral signs of anxiety and depression observed in Akt3 KO mice." (PMID 28442992, 2017). "Thus, GSK3β may play more important roles in depression than GSK3α." (PMID 34051074, 2021). "Moreover, GSK-3α and GSK-3β are activated in an environment of chronic oxidative stress, such as in BD, with greater activation in mania than in depression." (PMID 34295268, 2021). "Compared with non-depressed subjects, GSK3β activity was increased in the postmortem ventral PFC from subjects with depression, and GSK3α activity did not change." (PMID 34051074, 2021).
leukemia (7 papers, 2016 to 2025). A malignant (clonal) hematologic disorder, involving hematopoietic stem cells and characterized by the presence of primitive or atypical myeloid or lymphoid cells in the bone marrow and the blood. "As an example, GSK-3α knock-down reduced proliferation and caused spontaneous apoptosis, and potentiated bortezomib-induced toxicity, in leukemia cells." (PMID 27610044, 2016). "The results show that combined treatment with GO and GSK3α/β inhibitors enhanced apoptosis in leukemia cell lines." (PMID 36819180, 2023). "Loss of GSK-3α induces cell differentiation in AML, and a GSK-3β inhibitor suppresses cell growth and induces apoptosis in leukemia cells." (PMID 35008789, 2021). "Furthermore, Hinze and colleagues showed that GSK3α inhibition profoundly sensitized drug-resistant leukemias to asparaginase by phenocopying a Wnt pathway activation signal." (PMID 35710782, 2022). "Given our result that GSK-3α inhibition increased Akt phosphorylation, we speculate that there is a feedback loop between the PI3K/Akt pathway and GSK-3α for the regulation of NK activating ligands on leukemia cells." (PMID 33918810, 2021). "In this regard, targeted modulation of GSK-3α may hold promise as a viable strategy to improve NK cell reactivity against leukemia cells in addition to its direct anti-leukemic effects, given the upregulation of NKG2DL and NKp30L in leukemia cells upon GSK-3α inhibition." (PMID 33918810, 2021). "Moreover, as NKG2DL are frequently downregulated or absent on leukemia blasts and leukemic stem cells, the upregulation of B7-H6 by GSK-3α inhibition could provide an additional therapeutic target to enhance NK cell reactivity against leukemia cells." (PMID 33918810, 2021). "A GSK3α-selective compound, BRD0705, also showed to inhibit leukemia initiation and extend survival in an AML mouse model." (PMID 40805157, 2025). "We also checked the response of S6-ribosomal protein (rpS6), which is downstream Akt; of GSK3α/β, which are phosphorylated by Akt and ERK; and of p38-MAPK, also described as a target of quercetin or quercetin-derived analogs in leukemia cells." (PMID 27610044, 2016). "Thus, targeted inhibition of GSK-3α may provide an alternative therapeutic strategy against refractory/relapsed CML cells with TKI-resistance and possibly other leukemia cells in the context of NK cell-based therapy." (PMID 33918810, 2021). "A potential correlation with tivantinib sensitivity could be amplification of GSK3α expression levels as GSK3α is more highly expressed in several different subtypes of AML, including 11q23 MLL-rearranged leukemia, which has previously been shown to be sensitive to GSK3 inhibition." (PMID 30679640, 2019). "While GSK3α is less studied in the context of Wnt signaling, recent work has shown that selective inhibition of GSK3α (e.g., BRD0705) can suppress leukemia initiation without promoting β-catenin stabilization, offering a potentially safer therapeutic avenue." (PMID 40805157, 2025).
ovarian carcinoma (7 papers, 2014 to 2024). A malignant neoplasm originating from the surface ovarian epithelium. "Our risk model, composed of six proteins (GSK3α/β, HSP70, MEK1, MTOR, BAD, and NDRG1), can predict survival of ovarian cancer patients effectively, thereby helping prognosis monitoring and decision making." (PMID 35840928, 2022). "Because the expression of GSK-3 is significantly higher in ovarian carcinoma tissues, the significant reduction in GSK-3α and β expression in the current study after treatment with genistein indicates an anticancer effect." (PMID 33550763, 2021). "The drug-resistance-related genes ABCB1, ABCC1 GSK3A, had significantly higher expression levels in OCICs than in primary ovarian cancer cells." (PMID 25369529, 2014). "GSG2 mediates GSK3α to regulate cell cycle in epithelial ovarian cancer." (PMID 38613588, 2024). "Besides, GSG2 mediated GSK3α to modulate cell cycle and promote epithelial ovarian cancer cell proliferation." (PMID 38613588, 2024). "Therefore, we conjecture that GSG2 mediates GSK3α to regulate p27 expression in epithelial ovarian cancer." (PMID 38613588, 2024). "Although it is verified that GSK3β positively regulates the proliferation of human ovarian cancer cells, the association between GSK3α and ovarian cancer has not been demonstrated." (PMID 38613588, 2024). "The risk model composed of six proteins (GSK3α/β, HSP70, MEK1, MTOR, BAD, and NDRG1) could predict the survival prognosis of ovarian cancer efficiently and had a prominent predictive performance." (PMID 35840928, 2022). "GSK3α/β was found to be involved in tumor growth of ovarian cancer." (PMID 35840928, 2022). "The risk model composed of GSK3α/β, HSP70, MEK1, MTOR, BAD, and NDRG1 could predict survival prognosis of ovarian cancer patients efficiently and help disease management." (PMID 35840928, 2022).
cardiac hypertrophy (6 papers, 2011 to 2025). "In cardiac pathology, GSK3α enhances cardiomyocyte proliferation and ameliorates heart failure, while GSK3β is associated with cardiac hypertrophy and fibrosis." (PMID 41300341, 2025). "The deletion of GSK3α in mice was also reported to cause cardiac hypertrophy and contractile dysfunction." (PMID 38732116, 2024). "For example, phosphorylation and inhibition of GSK3α/β by PKB/Akt is a key element in the development of cardiac hypertrophy." (PMID 34002209, 2021). "It is reported that quercetin prevented cardiac hypertrophy by proteasome inhibition and activation of GSK-3α/β, which is related to upstream (AKT, LKB1/AMPKα) and downstream hypertrophic factors, such as ERK, histone H3, β-catenin, and GATA4." (PMID 31949472, 2019). "For example, it has been shown that up-regulation of GSK-3α inhibited cardiac growth and pressure overload-induced cardiac hypertrophy which is mediated through inhibition of ERK." (PMID 22028912, 2011). "GSK-3α is a less studied isoform, but studies suggest its involvement in the regulation of cell proliferation and differentiation, and its inhibition may be related to protection against cardiac hypertrophy and remodeling." (PMID 40869179, 2025).